TRIM49C (tripartite motif containing 49C)
Synonyms: TRIM49L2
Tractability: No criterion of Open Targets' tractability assessment is met for any kind of drug.
Gene: Protein-coding gene on chromosome 11 (90,031,106 to 90,042,025, forward strand). Ensembl gene ENSG00000204449.
Gene Ontology:
Molecular function: protein binding; ubiquitin protein ligase activity; zinc ion binding
Biological process: innate immune response; regulation of gene expression
Cellular component: cytoplasm
Genetic constraint (gnomAD): Loss-of-function variants: 2 observed, 7.68 expected, observed/expected ratio (o/e) 0.26, 90% interval 0.1 to 0.82. That is too few expected variants to judge how well the gene tolerates losing a copy. Missense variants: 133 observed, 272 expected, observed/expected ratio (o/e) 0.49, 90% interval 0.42 to 0.56. Synonymous variants: 46 observed, 86.62 expected, observed/expected ratio (o/e) 0.53, 90% interval 0.42 to 0.68.
Homologues: Paralogues in human: TRIM49 (99% identical), TRIM49B (95% identical), TRIM49D1 (85% identical), TRIM49D2 (85% identical), TRIM51 (75% identical), TRIM51G (71% identical), TRIM43 (52% identical), TRIM43B (52% identical), TRIM64 (46% identical), TRIM64B (46% identical), TRIM64C (45% identical), TRIM77 (43% identical), and 68 more.
Diseases named in the same sentence as TRIM49C in open-access papers:
TRIM49C is named in the same sentence as 1 disease in open-access papers, as found by Europe PMC text mining. Sharing a sentence is not in itself a finding about the gene and the disease.
TRIM49C shares sentences with these, for which no sentence is quoted: bladder cancer (1 paper).